LINC01447 (long independently transcribed non-coding RNA 1447)
Gene: Long non-coding RNA gene on chromosome 7 (47,608,256 to 47,629,899, forward strand). Ensembl gene ENSG00000236078.
Diseases named in the same sentence as LINC01447 in open-access papers:
LINC01447 is named in the same sentence as 1 disease in open-access papers, as found by Europe PMC text mining. Sharing a sentence is not in itself a finding about the gene and the disease. The quoted sentences say what the papers report.
glioma (1 paper, 2020). A benign or malignant brain and spinal cord tumor that arises from glial cells (astrocytes, oligodendrocytes, ependymal cells). "Taken together, these results show that downregulation of LINC01447 or AC106786.1 enhanced the radiosensitivity of low-grade glioma cells." (PMID 32453707, 2020).